DYRK1A (dual specificity tyrosine phosphorylation regulated kinase 1A)
Diseases named in the same sentence as DYRK1A in open-access papers (continued):
Sharing a sentence is not in itself a finding about the gene and the disease.
cancer (continued). "Therefore, uncovering the effect of DYRK1A on HCC tumorigenesis could help identify cancer patients who are most likely to benefit from treatment with DYRK1A inhibitors." (PMID 35655269, 2022). "Therefore, inhibition of DYRK1A has been reported to reduce cancer stem cell phenotype." (PMID 35454940, 2022). "However, DYRK1A expression levels vary among different types of cancer." (PMID 35454940, 2022). "Accordingly, compound 1g was found to inhibit TRKA (neurotrophic tyrosine receptor kinase 1, NTRK1), DYRK1A/1B (dual specificity tyrosine-phosphorylation-regulated kinase 1A and 1B), and CK1δ (casein kinase 1 delta, CSNK1D) kinases, reportedly associated with overexpression in cancer cells." (PMID 34959689, 2021). "In summary, and in contrast to the controversial role of DYRK1A in cancer, clear oncogenic facets have been attributed to DYRK1B, acting as a prosurvival factor that could help cancer cells survive in suboptimal growth conditions and preventing chemotherapeutic-induced DNA damage and apoptosis." (PMID 32751160, 2020). "The two phosphosites of FOXO1 found in this study are important for follicular development, prevent GCs from apoptosis, and may be valuable for developing compounds that disrupt the phosphorylation of FOXO1 by DYRK1A, which could serve as a potential choice for cancer-related drug design." (PMID 33520998, 2020). "Therefore, we hypothesized that DYRK1A suppression would sensitize cancer cells to Bcl-2 inhibitor treatment by suppressing Mcl-1 expression." (PMID 32587776, 2020). "In addition, DYRK1A suppression by siRNA or an inhibitor could increase the anti‐cancer activity of AZD9291 in EGFR wild‐type NSCLC cells." (PMID 31454149, 2019). "In a completely different context, the increased sensitivity of cells to DNA damage when DYRK1A is depleted could be therapeutically exploited for cancer treatment by combining DYRK1A inhibitors and genotoxic drugs in cancer types in which DYRK1A inhibitors have an impact on the tumoral cell." (PMID 30979931, 2019). "Scientists believe that DSCR1 and DYRK1A could be candidates for potential cancer therapy target." (PMID 29244857, 2017). "Our findings highlight a critical role for the DYRK1A/TSC2/mTORC1 signaling pathway in regulating cDC1 functions in antitumor immunity, offering potential strategies to improve cancer immunotherapy." (PMID 42024470, 2026). "DYRK1A and DYRK1B play key roles in neurodevelopment and cancer biology and are increasingly recognized as potential drug targets in disorders including Alzheimer’s disease, diabetes mellitus, metabolic syndrome, heart disease, and cancer." (PMID 41444824, 2025). "The mechanism by which DYRK1A regulates DREAM complex assembly is reported to function conservatively across various processes, including cancer, cellular aging, and regeneration." (PMID 39796178, 2025). "In this study, we employed A549 and PANC-1 cancer cell lines to explore the expression of DYRK1B and DYRK1A in response to serum deprivation and increased cell density." (PMID 39397076, 2024). "In the present study, we scrutinized the regulatory pathways modulating DYRK1B expression relative to DYRK1A in PANC-1 and A549 cancer cell lines across varying conditions." (PMID 39397076, 2024). "In summary, our findings indicate that the expression of DYRK1A and DYRK1B is differentially regulated in cancer cells and reveal that the kinase inhibitor XMU-MP-1 increases DYRK1B expression likely through off target inhibition of Aurora kinases." (PMID 39397076, 2024). "Most of the Dyrk1B inhibitors reported to date are proven effective in cancer treatment, but still exhibit off-target effects on other GMGC or DYRK kinases, and mainly on Dyrk1A, the closest member of Dyrk1B." (PMID 38675189, 2024). "Given the significance of ZBTB33/Kaiso function in the neurological processes and cancer, further investigation of the functional interaction between DCAF7, DYRK1A and Kaiso is justified." (PMID 37900285, 2023).
cancer (continued). "In cancer, DYRK3 was proposed to act in parallel with DYRK1A to promote cell survival under stressful conditions by phosphorylating nicotinamide adenosine dinucleotide (NAD)-dependent deacetylase SIRT1." (PMID 35454940, 2022). "The dual‐specificity tyrosine‐regulated kinases DYRK1A and DYRK1B play a key role in controlling the quiescence‐proliferation switch in cancer cells." (PMID 34708541, 2021). "Oncogenic receptor tyrosine kinases, RAS/MAP kinase, PI3K/AKT/S6K, DYRK1A, PKC and histone deacetylases can enhance the transcriptional activity of GLI in human cancer cells." (PMID 26784250, 2016). "DYRK1B, the closest homologue of DYRK1A, can act downstream of RAS to prevent autocrine and promote paracrine HH signaling in RAS mutant cancer cells." (PMID 26784250, 2016). "Here, we demonstrate that expression of DYRK1B - but not its closely related paralog DYRK1A - is upregulated by cytostatic drugs (Actinomycin D, Doxorubicin) in multiple cancer cell lines." (PMID 41888523, 2026). "This study suggests that Catechin gallate may have a strong binding affinity for DYRK1A and FUT4, indicating its potential for treating other diseases, such as cancer and neurodegenerative disorders." (PMID 40699724, 2025). "The gene copy number variation data is supported by analysis of the RNA sequencing data, which also indicates a significant downregulation of DYRK1A in most, but not all cancer types." (PMID 37900285, 2023). "Additionally, the gene targets of these miRNAs included several cancer driver genes including ZNF704 (targeted by ten miRNAs), MMP16 (targeted by eight miRNAs), and KCNN3, POU2F1, ADARB1, MPZL1, RUNX1T1, UBE2W, and DYRK1A genes (targeted by seven miRNAs)." (PMID 37685851, 2023). "In a different context, defects in protein production are closely related to cancer, since enhanced translation is required to boost cell proliferation and DYRK1A has both positive and negative effects on cell proliferation, depending on the tumor context." (PMID 38254631, 2023). "This indicates that expression of DYRK1A, but not other DYRK members, can predict cancer survival in CRC." (PMID 35454940, 2022). "Against this background, DYRK1A is well known to phosphorylate Ser28 in LIN52, an event that converts the proliferative MMB configuration to the repressive DREAM complex, thereby inducing cell cycle arrest or quiescence in many cancer cell types." (PMID 35700053, 2022). "Dual-specificity tyrosine phosphorylation-regulated kinase 1A (DYRK1A) regulates neural progenitor cell differentiation, but its role in cancer stem cell differentiation is largely unknown." (PMID 33924599, 2021). "DYRK1A regulates other cell factors known to participate in malignant transformations, including the stemness-related RE1 silencing transcription factor REST or key effectors of cancer-promoting signaling pathways, like the Hh, Wnt and Notch pathways." (PMID 32751160, 2020). "A series of factors such as oncogenic receptor tyrosine kinases, RAS/MAP kinase, PI3K/AKT/S6K, DYRK1A, PKC, TGF-β, and histone deacetylases could enhance the transcriptional activity of GLIs in human cancer cells." (PMID 31427566, 2019). "Although the cause was still unclear, it had been proposed that the DS patients might get extra doses of one or multiple cancer-suppressor genes such as DSCR1 and DYRK1A due to the extra copy of chromosome 21." (PMID 29351810, 2018). "Taking also into account that, besides CK2, it inhibits PIM-1 (a very important and innovative target in cancer therapy), CLK2, and, with lower efficacy, also DYRK1A, we believe that TDB displays good features to be considered for future clinical experimentation." (PMID 26558259, 2015).
cancer (continued). "Interestingly, the model’s predicted effect of DYRK1A KO on DNA replication was consistent with cardiomyocyte literature but not consistent with cancer literature." (PMID 40901489, 2025). "DYRK1A is not a common essential gene validated via the Cancer Dependency MAP website, indicating that targeting DYRK1A may represent a target with a unique therapeutic window." (PMID 40148558, 2025). "Thus, these novel scaffolds present a potential new avenue for therapeutic development targeting Dyrk I class in cancer, but they do not solve the problem of selectivity between Dyrk1A and Dyrk1B kinases." (PMID 38675189, 2024). "The role of DYRK1A in cancer is not well studied and remains controversial." (PMID 38839871, 2024). "Thus, these phosphorylation modifications of NPF and regulatory factors that can phosphorylate NPF, such as Shp1, Dyrk1A, Casein Kinase II, PAK4, SRC, ERK, Abl, Cdk5, etc., may provide targets for anti-invasive cancer therapy." (PMID 37026902, 2023). "The general trend towards a reduced DYRK1A expression in tumor samples would be in agreement with a more prominent tumor-suppressor role, even though the correlation between DYRK1A mRNA and the protein levels has not been properly evaluated in any cancer study." (PMID 32751160, 2020). "A recent review of DYRK1B has offered extensive information on this kinase, and thus, here, we will focus on those aspects of the kinase that are related to its role in cancer, which, unlike DYRK1A, point mostly to a prosurvival and protumorigenic role for DYRK1B." (PMID 32751160, 2020). "Therefore, in addition to helping understand the regulation of EGFR in cancer cells, our finding of MDM2 as a negative regulator of DYRK1A may also bear implications in the management of the conditions associated with DYRK1A overexpression." (PMID 30910997, 2019). "Also, HOPX was correlated with genes in a manner toward suppression of cancer cell progression; downregulation of TNRC6C, PAX8, TSHR, DYRK1A/B, and SLIT3 (pro-proliferation/migration), and upregulation of PCDH8/9, CDC42EP3/4/5, and TJP3 (anti-proliferation/migration)." (PMID 31666923, 2019). "A brief analysis of human PDA tissue samples indicated that these expression patterns in cells may correlate with expression in human cancer, with the exception of DYRK1A, which is not expressed in cancer tissue, but highly upregulated in cultured cell lines." (PMID 31719634, 2019). "Although the role of DYRK1A in cancers has been characterized, its role in HNSCC is not defined." (PMID 27796319, 2016). "DYRK1A has been shown to suppress caspase-9-mediated apoptosis in mammalian cells through phosphorylation of caspase-9 on threonine residue 125.22, 23 These findings suggest that SAHA and DZNep induce DYRK1A-mediated apoptosis in cancer cells through activation of miR-1246." (PMID 24861464, 2014). "The role of DYRK1A in the HPV16/18 infection and cancer pathogenesis is not well understood and appears to be contrary to its cell cycle control function." (PMID 37900285, 2023). "As the consequence of DYRK1A decreases, NFATC1, a target of DYRK1A, was no longer exported out of the nucleus leading to dramatic cell apoptosis in cancer cells." (PMID 34828439, 2021). "It was also suggested by other researchers that the anti-cancer activities of EGCG and green tea might not be limited to DYRK1A inhibition, but their proven safety over the history makes them good drug candidates." (PMID 33860868, 2021).
tumor (71 papers, 2012 to 2026). "As described in the next section, these observations agree with a previous report supporting a prominent role for DYRK1A as a potent megakaryoblastic tumor-promoting gene that contributes to DS-associated AMKL leukemogenesis." (PMID 40519271, 2025). "The HSA21-encoded gene DYRK1A is associated with several malignancies, both tumor promoting and tumor suppressing, and has been specifically implicated in ML-DS pathogenesis in a murine model." (PMID 37906251, 2023). "Although current evidence has highlighted the importance of DYRK1A in tumour metastasis, its promoting effects on tumour metastasis, as well as the underlying mechanism, need further investigation." (PMID 35655269, 2022). "Tumor samples with high DYRK1A were found to be significantly associated with mucinous colorectal adenocarcinoma cancer." (PMID 35454940, 2022). "Although T‐025 potentially inhibits other kinases, particularly for DYRK1A, we hypothesize that the anti‐tumor effects of T‐025 were caused via CLK inhibition." (PMID 29769258, 2018). "Genetic ablation of Dyrk1a specifically in cDC1s impaired antitumor immunity and accelerated tumor progression in murine models." (PMID 42024470, 2026). "Cell-based experiments demonstrated that DYRK1A was a potent megakaryoblastic tumor-promoting gene that contributes to leukemogenesis through dysregulation of NFAT signaling." (PMID 40519271, 2025). "Our study, therefore further advocates for the development of pre-clinical studies aimed at testing DYRK1A inhibitors as potential chemo-sensitizers, to enhance the anti-tumor activity of irinotecan against human models of CRC." (PMID 39896677, 2025). "In contrast, DYRK1A can also function as a tumor suppressor by arresting the cell cycle and inhibiting proliferation." (PMID 40723805, 2025). "Combined, these results highlight DYRK1A as a central regulator of both primary tumor formation and metastatic spread to distant organs." (PMID 38839871, 2024). "Similar to what observed on primary tumor formation, we found that DYRK1A gene silencing and topotecan treatment alone showed a significant reduction in lung nodule formation." (PMID 38839871, 2024). "To further address this, we analyzed the protein expression levels of various EMT markers in the resected tumors from the NT and DYRK1A KO tumor samples from the MDA-MB-231 xenografts." (PMID 38839871, 2024). "The role of DS critical region in tumor suppression is strongly supported by studies using animal models, although the contribution of the individual genes, including DYRK1A, remains to be further investigated." (PMID 37900285, 2023). "The function of DYRK1A in the regulation of cell-cycle events was shown previously in tumor, neuronal, fibroblastic, and pre-B cells." (PMID 36927854, 2023). "In preclinical lung cancer tumor models, inhibition of DYRK1A results in decreased STAT3/EGFR/Met signaling and NSCLC sensitization to EGFR inhibitor AZD9291 (Li YL." (PMID 37900285, 2023). "In the same study, the treatment with DYRK1A inhibitor Harmine as a single agent increased the survival of tumor-bearing animals." (PMID 37900285, 2023). "Several studies have indicated that DYRK1A acts as a tumour suppressor gene, while others have highlighted its pro-oncogenic activity." (PMID 35655269, 2022). "In correlation with DYRKs expressions in CRC subtypes, DYRK1A and 3 significantly correlated with tumor infiltrating immune cells; this suggests that those two kinases can act as a prognostic marker for MSI and immunotherapy response." (PMID 35454940, 2022). "Based on mRNA level, DYRK1A is upregulated in late tumor stages, with lymph node and distant metastasis." (PMID 35454940, 2022).
tumor (continued). "From these evidences, we suspect that ACB-1801 increases tumor antigen presentation most likely through its potent property to inhibit DYRK1A and revert tumor malignant phenotype." (PMID 36458012, 2022). "Based on mRNA level, DYRK1A is the only member of DYRKs that was found to be upregulated in late tumor stages, with lymph node and distant metastatic stages." (PMID 35454940, 2022). "Both tumour suppressive and oncogenic functions have been reported for dual-specificity tyrosine phosphorylation-regulated kinase 1A (DYRK1A)." (PMID 33863878, 2021). "DYRK1A expression is regulated by transcriptional factors, tumor suppressors, neurogenic factors, and protein-protein interactions." (PMID 34445786, 2021). "To investigate the effect of DYRK1A inhibition in a tumour microenvironment with biological relevance, we measured the effects of EGCG on the viability of 3D structures formed by SY5Y in a Matrigel-based 3D sandwich culture system." (PMID 33860868, 2021). "We recognised that the clear mechanism of EGCG acting on tumours either DYRK1A dependent or involving other pathways worth further studying." (PMID 33860868, 2021). "In summary, these results demonstrate the potential of DYRK1A/B inhibition to push tumour cells back into the cell cycle and hence re‐sensitize to chemotherapy or targeted therapies." (PMID 34708541, 2021). "DYRK1A is also overexpressed in multiple human malignancies, including hematological and brain cancers, where it contributes to tumor growth by manipulating cell cycle progression." (PMID 32587776, 2020). "Overexpression of lncRNA OIP5-AS1, as well as DYRK1A, facilitates apoptosis of tumor cells after irradiation." (PMID 32122355, 2020). "In pancreatic ductal adenocarcinoma (PDAC) tumor tissue, a similar relationship was found between the expression of DYRK1A and c-MET, the hepatocyte growth factor receptor." (PMID 32751160, 2020). "Both tumor-suppressive and pro-oncogenic roles have been suggested for DYRK1A, especially in relation to brain tumors." (PMID 31035417, 2019). "Consistent with the potential role of DYRK1A in angiogenesis, the TS65Dn mouse model of DS, trisomic for the Dyrk1a gene, exhibited reduced tumor growth, presumably by suppressing tumor angiogenesis." (PMID 31043432, 2019). "Our findings have broad therapeutic implications related to roles for DYRK1A as a tumor suppressor and mediator of radiosensitivity." (PMID 31024071, 2019). "Further, administration of the small molecular inhibitor against DYRK1A in mice bearing HNSCC xenograft tumors induced regression of tumor growth." (PMID 27796319, 2016). "Immunohistochemical labeling of DYRK1A in primary tumor tissues using tissue microarrays revealed strong to moderate staining of DYRK1A in 97.5% (39/40) of HNSCC tissues analyzed." (PMID 27796319, 2016). "Furthermore, they also indicate that DYRK1A inhibition potently decreases tumor growth and efficiently prevents the formation of liver, kidney, and lung metastatic nodules." (PMID 38839871, 2024). "DYRK1A could contribute to the DS tumor suppression though its role in cellular senescence, a distinct type of cell cycle arrest that prevents the expansion of cells that acquired an oncogenic mutation." (PMID 37900285, 2023). "Moreover, tumor samples with higher DYRK1A level exhibited higher tumor recurrence following initial therapy, whereas none of the other DYRKs members showed any significant change." (PMID 35454940, 2022). "DYRK1A is significantly upregulated in late tumor stages from IIIA to IVB." (PMID 35454940, 2022). "Some of the candidate genes implicated were studied in mice, although single-gene perturbations did not explain all of the angiogenic phenotypes in Ts65Dn mice; overexpression of RCAN1 and DYRK1A were reported to affect proliferation, vascular structures, and tumor allografts." (PMID 35947952, 2022).